GSK3B (glycogen synthase kinase 3 beta)
Diseases named in the same sentence as GSK3B in open-access papers (continued):
Sharing a sentence is not in itself a finding about the gene and the disease.
Insulin resistance (continued). "This insulin-induced hyper-phosphorylation of AKT1 and GSK-3β was significantly reduced in KO mice as assessed using western blotting, which implied that mild insulin resistance was induced in KO mice." (PMID 30485307, 2018). "Further studies are necessary to address this point and to determine the involvement of GSK-3β signaling deregulation in the insulin resistance development in GK rats." (PMID 29220408, 2017). "Baicalin also attenuates high-fat diet-induced insulin resistance and ectopic fat storage in the skeletal muscle, by modulating the protein kinase B/glycogen synthase kinase 3 beta pathways." (PMID 28951767, 2017). "Palmitate induced insulin resistance as indicated by impaired insulin-induced phosphorylation of insulin receptor, Akt, Gsk3β and FoxO1." (PMID 28933767, 2017). "Abnormalities in the signaling pathway, including IRS1, FOXO1 and GSK3β, marked the main characteristics of insulin resistance in Huh7-Pre-miR190b-6 cells." (PMID 24586785, 2014). "Activation of glycogen synthase kinase 3β (GSK-3β) which has a pivotal role in promoting Tau hyper-phosphorylation, is a major consequence of impaired insulin signaling and insulin resistance." (PMID 25035815, 2013). "GSK-3B has long been known as an important mediator for impaired insulin action on peripheral tissue and in the development of insulin resistance." (PMID 20942928, 2010). "Therefore, inhibition of GSK3β activity to modulate insulin resistance has become one of the important strategies for treating Type 2 Diabetes." (PMID 40692617, 2025). "Additionally, insulin resistance leads to the activation of glycogen synthase kinase-3β (GSK-3β), a key enzyme responsible for tau hyperphosphorylation, contributing to the formation of neurofibrillary tangles." (PMID 40724831, 2025). "Besides, it has been reported that increased p-IRE1/IRE1 and p-GSK-3β/GSK-3β levels were closely related to insulin resistance, and the inhibition of insulin resistance can be induced by regulating IRE1/GSK-3β axis." (PMID 39791173, 2025). "As the elevated GSK3β activity could be restored by liraglutide treatment the reversibility of insulin resistance was also confirmed." (PMID 40724831, 2025). "Concomitantly, calycosin elevates the insulin-sensitizing proteins Glucose transporter 4 (Glut-4) and Glycogen synthase kinase 3 beta (Gsk3β), enhancing peripheral glucose uptake and glycogen synthesis, thereby ameliorating both glucose tolerance and insulin resistance." (PMID 41463300, 2025). "Insulin resistance leads to dysfunctional Akt signaling and activation of GSK3β." (PMID 38581667, 2024). "Moreover, the hepatic Zbtb18 rescue improved the glucose intolerance and insulin resistance of Zbtb18LKO mice, also beneficially inducing enhanced phosphorylation of AKT and GSK-3β in Zbtb18-deficient liver." (PMID 38263084, 2024). "Insulin resistance, not treated in both groups given nifedipine, was associated with high levels of GSK3β and low levels of IDE." (PMID 39204160, 2024). "In a 12-week randomized controlled trial, participants with prediabetes who consumed 180 mg of curcumin daily had significantly reduced GSK3β and IAPP in serum samples after 12 weeks compared with placebo groups, reducing insulin resistance and the risk of developing AD and DM." (PMID 36909158, 2023). "Likewise, Cd exposure seems to be an inductor of the activity of GSK3β or an inhibitor of GS because animals exposed to a chronic environmental LOAEL dose show insulin resistance and continuous reduction in hepatic glycogen levels." (PMID 36976988, 2023). "And it can mediate cerebral insulin resistance and inhibit Akt/GSK3β." (PMID 36909158, 2023). "Since basal Akt activity phosphorylates and deactivates GSK3β, we hypothesized that insulin resistance likely led to an activation of GSK3β, which induced ADAM10/17 and VCAM1 expression." (PMID 37762417, 2023).
Insulin resistance (continued). "The activated form of Akt, phosphorylated Akt (p-Akt), may inhibit several proapoptotic factors including glycogen synthase kinase-3 beta (GSK3β), which in turn mediates insulin resistance and human type 2 diabetes." (PMID 36769365, 2023). "Insulin resistance and hyperinsulinemia increase the levels of intracellular and extracellular Aβ, resulting in Aβ accumulation and abnormal tau phosphorylation via the insulin-signaling activation of the GSK-3b cascade." (PMID 35682821, 2022). "3,3′,4,5′-TMS ameliorated insulin resistance by enhancing the phosphorylation of glycogen synthase kinase 3 beta (GSK3β), inhibiting phosphorylation of insulin receptor substrate-1 (IRS-1), and activating phosphatidylinositol 3-kinase (PI3K)/protein kinase B (Akt) pathway in IR-HepG2 cells." (PMID 35678676, 2022). "Defective central insulin signaling secondary to obesity‐related peripheral insulin resistance may induce tau phosphorylation via activation of GSK‐3β." (PMID 35662390, 2022). "Interestingly, GSK3-β can also be activated by oxidative stress, which is a consequence of insulin resistance." (PMID 34576151, 2021). "Moreover, loganin attenuated insulin resistance by modulating the JNK-IRS-1 (insulin receptor substrate-1)-Akt-GSK3β signaling pathway in PDN rats." (PMID 34685668, 2021). "The present results on tilapia showed that rosiglitazone in the HC diet could promote the phosphorylation of Akt and GSK‐3β, promote the synthesis of liver glycogen, reduce the level of blood glucose, and also alleviate the liver insulin resistance." (PMID 33650786, 2021). "In addition, Ex-4 improved the basal expression of IRS-1 and GSK-3β phosphorylation in neurons under PA-induced insulin resistance, compared to the control group." (PMID 33435277, 2021). "Moreover, Aβ and insulin resistance suppress phosphatidylinositol-4,5-bisphosphate 3-kinase- (PI3K-) Akt signaling leading to activation of GSK-3β and mTOR, which in turn causes PP2A inhibition and subsequent tau hyperphosphorylation." (PMID 34306309, 2021). "Insulin resistance promotes oxidative stress through several routes such as the dysregulation of carbohydrate and lipid metabolism, increased GSK-3β activation, and the impairment of cell survival and anti-apoptotic signaling, energy balance and mitochondrial function." (PMID 34576151, 2021). "Insulin resistance leads to a reduction in the activation of protein kinase B, a protein that holds an important role in glucose metabolism and the inhibition of glycogen synthase kinase 3 beta (GSK3β), a main kinase that phosphorylates the tau protein." (PMID 34867762, 2021). "In addition, old rats also showed increased serum levels of insulin and HOMA-index, and reduced expression of GCK and GSK3β in the liver, which denotes a state of insulin resistance, another important feature of metabolic aging." (PMID 32503213, 2020). "Given that the enhanced activation of NF-κB pathways could induce insulin resistance by the dephosphorylation of Akt and GSK-3β, we assessed the effects of Sennoside A on the related pathways." (PMID 32685087, 2020). "TLR4 signaling pathways can induce the production of proinflammatory cytokines by modulating the activity of NF-κB, and the enhanced activation of NF-κB pathways may induce insulin resistance via the dephosphorylation of Akt and GSK-3β." (PMID 32685087, 2020). "The main components of EGb may act on multiple targets, such as PTGS2, PPARG, DPP4, and GSK3B, to regulate multiple pathways, and play an antiaging role by inhibiting oxidative stress, inhibiting inflammation, and ameliorating insulin resistance." (PMID 32802136, 2020). "The present study provides evidence supporting the idea that hyperinsulinemic condition causes neuronal insulin resistance as indicated by the decreased phosphorylation of insulin receptors and their downstream signaling molecules, including IRS-1, AKT/PKB, and GSK-3β." (PMID 32138327, 2020).
Insulin resistance (continued). "In addition, the MH treatment of DCM mice significantly improved their insulin resistance levels by activation of GSK‐3β." (PMID 31199069, 2019). "In insulin resistance, GSK3β is increased leading to increased blood glucose." (PMID 31614723, 2019). "Also, insulin resistance dysregulates the PI3K/AKT/GSK-3β signaling cascade and generates hyperphosphorylated tau." (PMID 29950970, 2018). "However, under conditions of insulin resistance, GSK-3β is converted to its active form by phosphorylation at Tyrosine-216 residue." (PMID 29950970, 2018). "The previous study suggested that GSK3β activity be increased in skeletal muscle samples from subjects with insulin resistance and that phosphorylated (inactive) GSK3β expression was lowered in skeletal muscle obtained from women with GDM, which are consistent with our results." (PMID 29677194, 2018). "Mechanistically, STAT3-AR co-binding stimulated by CCRK transcriptionally activates its own promoter, which in turn triggers the mTORC1/4E-BP1/S6K/SREBP1 cascades via GSK3β phosphorylation to augment hepatic lipid accumulation, glucose intolerance, insulin resistance, and tumorigenicity." (PMID 30523261, 2018). "Interestingly, both strategies abrogated hepatic insulin resistance and mitochondrial dysfunction, presented by enhanced p-Akt and p-GSK3β, reduced p-JNK signaling, along with p-AMPK and PGC-1α activation." (PMID 29163785, 2017). "Moreover, high glucose induced insulin resistance by decreasing the phosphorylation of GSK3β, triggering the ubiquitination and degradation of insulin receptor substrate (IRS1), which did not require insulin receptor signaling or PI3K/AKT activity." (PMID 25993471, 2015). "Moreover, GSK3β is a major factor in insulin resistance via its role in the regulation of the insulin signaling pathway." (PMID 26296196, 2015). "Interestingly, inactivation of SphK1 augmented the effect of PA induced insulin resistance in L6 myotubes, which was associated with further inhibition of insulin stimulated PKB and GSK3β phosphorylation, glucose uptake and the accumulation of sphingosine." (PMID 24376889, 2013). "Having confirmed the development of hepatic insulin resistance (impaired glucose tolerance and the blunted insulin-stimulated phosphorylation of Akt and GSK3β in the liver), we next investigated the involvement of JNK and IKK as mediators of steatosis and insulin resistance." (PMID 22355328, 2012). "Further experimentation perhaps employing other methods of analysis or approaches is necessary to better understand how changes in the basal phosphorylation of p70S6k, mTOR, Akt, and GSK-3β may contribute to pathophysiology of insulin resistance." (PMID 20368999, 2009). "However, in patients with type 2 diabetes, the activity of GSK3β is abnormally elevated, leading to excessive inhibition of GS activity, reduced glycogen synthesis, and consequently, elevated blood glucose levels, a phenomenon known as insulin resistance." (PMID 40692617, 2025). "Furthermore, pancreatic islet cells isolated from these Pb-treated rats exhibited reduced cell viability and impaired glucose-stimulated insulin secretion (GSIS), which was associated with increased ROS levels and elevated glycogen synthase kinase-3 beta (GSK-3β), contributing to insulin resistance." (PMID 40408591, 2025). "Another study also found that QWBZS alleviated insulin resistance in diabetic encephalopathy (DE) rats by a mechanism that may be related to the repair of hippocampal neuronal damage in DE rats by activating the PI3K/Akt/GSK-3β signaling pathway." (PMID 39845797, 2024). "Fisetin supplementation could ameliorate hyperlipidemia and insulin resistance through regulating the IRS1Tyr608/AKT/GSK3β/FoxO1 signaling pathway, the expression of phosphorylated IRS1Tyr608, AKT, FoxO1 and GSK3β was markedly decreased by the intervention of fisetin in the kidneys of HFD-fed mice." (PMID 38799166, 2024).
Insulin resistance (continued). "Furthermore, L-50 could return insulin resistance to a normal homeostasis, possibly attenuating oxidative stress by reducing the accumulation of ROS, as well as engaging the JNK/AKT/GSK3β protein signaling pathway to alleviate insulin resistance." (PMID 37927560, 2023). "Importantly, abrogation of the GSK3β-mediated ERRα phosphorylation at S19, S22 and S26 in vivo led to altered insulin-dependent liver and muscle transcriptomes, compromised metabolism and insulin resistance." (PMID 35440636, 2022). "Interestingly, podocyte GSK3β is evolutionarily conserved to regulate the kidney function, and mice with podocyte-specific insulin resistance develop albuminuria and glomerular lesions, suggesting that GSK3β dysregulation plays a critical role in the pathogenesis of DN." (PMID 33562139, 2021). "Furthermore, insulin resistance results in activation of GSK3β (a principle kinase involved in tau hyperphosphorylation, and which is also known as tau kinase I), thereby contributing to the generation of more amyloid and tau pathology in a positive feedback cycle." (PMID 33921683, 2021). "Indeed, insulin resistance is an increasingly relevant risk factor of PD, and administration of insulin has been reported to alleviate cognitive impairment in a 6-OHDA-induced PD model through reducing the levels of p-AKT and p-GSK3β." (PMID 34567221, 2021). "Furthermore, we and others have reported that beyond its implication in insulin resistance in target tissues, GSK3β acts as a negative regulator of β-cell growth and function, thus further implicating this enzyme in the relative insulin deficiency associated with T2D." (PMID 31293498, 2019). "We may speculate that downregulated GSK-3β activity by vitamin D supplementation could lead to less NF-κB activation, decreasing cytokine production and thus, forming a feed-forward mechanism and further reducing the development of insulin resistance." (PMID 29342166, 2018). "Therefore, dysregulation of GSK-3β could result in attenuating insulin signaling, which was thought to induce insulin resistance." (PMID 25157753, 2014). "Other than an enhancement of glucose uptake, Akt phosphorylation also involves in GSK3-dependent pathway which responsible for glycogen synthesis and it was reported that HCV-induced insulin resistance may be through impairment of insulin-induced GSK3β phosphorylation." (PMID 22721429, 2012). "In summary, sinapine was confirmed to improve insulin resistance by upregulating the mRNA expression of IRS1, PI3K, AKT, GSK3β and GS and interacting with the target proteins to affect their phosphorylation." (PMID 41497732, 2026). "Based on our results we recognize the value of incorporating metabolic data—such as body weight, caloric intake, and insulin levels—as well as brain insulin resistance markers (e.g., phospho-IRS, phospho-AKT, and phospho-GSK3β)." (PMID 40948809, 2025). "Starting with the HYPO, we noticed signs compatible with insulin resistance in HFHFD-fed animals, which provoked an increased expression of IRβ, chronic activation of PI3K, and decreased activity of GSK3β." (PMID 40141063, 2025). "Insulin resistance and decreased insulin or IGF-1 levels affect Akt phosphorylation and phosphorylated GSK3β levels, which promote the breakdown of β-catenin." (PMID 40725728, 2025). "BBR improves glucose and lipid metabolism in obese mice through the reduction of IRE1/GSK-3β axis-mediated inflammation, showing the great potential of BBR in reversing insulin resistance in obesity." (PMID 39791173, 2025). "On the other side, insulin resistance impairs the PI3K/AKT signaling pathway, leading to the activation of GSK-3β and NF-κB and further resulting in increased apoptosis, autophagy, oxidative stress, and mitochondrial dysfunction." (PMID 39847072, 2025).
Insulin resistance (continued). "Specifically, regarding genes related to insulin resistance pathway, we highlight SOCS3, GSK3B, STAT3, PTEN, TRIB3, FOXO1, and PTPRF, along with MAPK8, which plays a role in metabolic stress and inflammation." (PMID 41282288, 2025). "The involvement of insulin resistance was studied by assaying glucose uptake and determining its IC50 values for cell viability improvement and GSK3β phosphorylation." (PMID 40724831, 2025). "During the development of insulin resistance, the levels of GSK-3β in skeletal muscle of mice significantly increased, while P-GSK-3β significantly decreased, indicating a gradual decrease in glycogen synthesis ability in skeletal muscle." (PMID 39761309, 2025). "Reversion to the ND improved insulin resistance and lipid profile, besides brain-derived neurotrophic factor (BDNF), glycogen synthase kinase-3 beta (GSK3β), and insulin-degrading enzyme (IDE) levels." (PMID 39204160, 2024). "Further, it improves liver insulin resistance in db/db mice and alleviates T2DM by regulating IRS1/PI3K/AKT/GSK3β signaling pathway." (PMID 38799166, 2024). "In another study, beyond increasing oxidative stress, glucose tolerance, and insulin resistance, 30 mg/kg/d microplastic exposure also led to decreased phosphorylation levels of AKT and GSK3β." (PMID 38251002, 2024). "One of the key characteristics of insulin resistance is impaired signal transduction of the insulin/PI3K/Akt signaling pathway, which leads to an increase in GSK-3β." (PMID 38683825, 2024). "Knockout of SARM1 in mice leads to a significant activation of insulin resistance-related pathways including AKT, GSK3β, IRS1, and FOXO1, thereby alleviating insulin resistance in mice fed a high-fat diet." (PMID 39021599, 2024). "One of the major hallmarks of insulin resistance is impaired signal transduction in the insulin/PI3K/Akt signaling pathway, leading to an increase in GSK-3β." (PMID 38683825, 2024). "Our results indicate that, in the brain, miR-153 is involved in CS-induced neuron insulin resistance and in a disorder of the PI3K/GSK3β/Tau pathway." (PMID 38133370, 2023). "In particular, after TAC/MSCH (100 mg/kg TAC/13 μg/kg MSC) administration, the phosphorylation of GSK3β and AKT was remarkably increased compared to that in the TAC-H group, which proves that MSC can promote the TAC effect on improving insulin resistance." (PMID 37513373, 2023). "Here the authors report that insulin-dependent dephosphorylation stabilizes ERRα via the GSK3β/FBXW7 axis, and disruption of this post-translational mechanism results in insulin resistance in mice." (PMID 35440636, 2022). "In contrast, TLB markedly mitigated insulin resistance in KK-Ay mice by reversing the changes of GLUT-2, p-IRS-1, p-Akt, and p-GSK-3β." (PMID 35153796, 2022). "Increased GSK3β protein expression and decreased GSK3β protein phosphorylation are often observed in T2DM animals with insulin resistance." (PMID 35267269, 2022). "The results of our study suggest that HAS reduces hepatic insulin resistance and increases hepatic glycogen synthesis by activating the PI3K/Akt/GSK-3β/GS signaling pathway." (PMID 36582530, 2022). "GSK3β was reported to be significantly increased in patients with T2DM and was positively correlated with insulin resistance." (PMID 36618687, 2022). "Insulin resistance is defined as a blunting of the PI3K insulin signaling pathway and chronic overactivation of GSK3β is an expected outcome of this state." (PMID 36038539, 2022). "Taken together, these results suggest that TBHQ activates the β-arrestin-2 factor to improve the protein expression of GLUT4, GSK3β, p-PI3K, and p-AKT in case of insulin resistance." (PMID 35096302, 2021). "We then evaluated the insulin resistance in the mouse hippocampus by measuring the degree of phosphorylation of IRS-1, AKT, and GSK-3β using western blot analysis." (PMID 33859286, 2021).